CAVIN1 (caveolae associated protein 1)
Diseases named in the same sentence as CAVIN1 in open-access papers (continued):
Sharing a sentence is not in itself a finding about the gene and the disease.
myopathy (9 papers, 2010 to 2025). A disease of the muscle in which the muscle fibers do not function properly. "Mutations in polymerase I and transcript release factor (PTRF/CAVIN1) were reported in five Japanese patients presenting with myopathy and CGL (CGL4)." (PMID 39874659, 2025).
infection (3 papers, 2017 to 2025). The state of being infected such as from the introduction of a foreign agent such as serum, vaccine, antigenic substance or organism. "We concluded that RSV infection alters the stoichiometry of the 80S-CCC by stabilizing cavin-1 protein during infection." (PMID 28154158, 2017). "Additionally, genes related to cell adhesion such as ADGRF5, CAVIN2, FAT3, FILIP1, GSN, and TSPAN11 were downregulated in both the variants at 24hpi whereas CAV1, CAVIN1, GPC3, POSTN, SUSD2, and TSPAN7 were downregulated only after Delta variant infection at 24 hpi." (PMID 41200555, 2025). "Similarly, Cavin1 appeared to be silenced following infection." (PMID 32678312, 2020).
cardiac disease (2 papers, 2012 to 2023). "Importantly, this analysis highlighted new potential dystrophin-associated proteins that were specific to cardiac DYS-IPs and involved proteins with known associations to cardiac disease in humans: Cavin-1 (PTRF), Ahnak1 (desmoyokin), Cypher (LDB3, ZASP), and Crystallin alpha B (CRYAB)." (PMID 22937058, 2012).
kidney disease (1 paper, 2017). "The repressive effect of H2O2, especially on caveolin-2/CAV2, PTRF/CAVIN1 and SDPR/CAVIN2 protein levels and the lack of effect on caveolin-1/CAV1 protein, argued against a major role of oxidative stress in induction of caveolar proteins in kidney disease." (PMID 29065889, 2017).
CAVIN1 also shares sentences with these, for which no sentence is quoted: Arrhythmia (4 papers); diabetes (4); lung adenocarcinoma (4); adenocarcinoma (3); Cerebral ischemia (3); hyperinsulinism (3); breast tumor (2); Cirrhosis (2); colorectal tumor (2); congenital generalized lipodystrophy (2); congenital generalized lipodystrophy type 3 (2); dyslipidemia (2); familial partial lipodystrophy (2); gastric cancer (2); metabolic disease (2); muscular hypertrophy (2); Non-alcoholic fatty liver disease (2); ovarian carcinoma (2); partial lipodystrophy (2); rhabdomyosarcoma (2); achalasia cardia (1); acquired lipodystrophy (1); Alzheimer disease (1); astrocytoma (1); autoimmune (1); bacterial infection (1); benign prostatic hyperplasia (1); Berardinelli-Seip congenital lipodystrophy type 2 (1); CANDLE syndrome (1); caveolinopathy (1).
A further 46 diseases each share a sentence with CAVIN1 in 1 paper.